LINC01354 (long independently transcribed non-coding RNA 1354)
Gene: Long non-coding RNA gene on chromosome 1 (234,502,343 to 234,532,575, reverse strand). Ensembl gene ENSG00000231768.
Diseases named in the same sentence as LINC01354 in open-access papers:
LINC01354 is named in the same sentence as 9 diseases in open-access papers, as found by Europe PMC text mining. Sharing a sentence is not in itself a finding about the gene and the disease. The quoted sentences say what the papers report.
colorectal cancer (5 papers, 2019 to 2022). A primary or metastatic malignant neoplasm that affects the colon or rectum. "LINC01354 acts as a ceRNA to predict the early diagnosis and prognosis of colorectal cancer." (PMID 31558162, 2019). "In colorectal cancer, HNRNPD interacts with LINC01354 and contributes to proliferation and metastasis through the activation of the Wnt/β-catenin signaling pathway." (PMID 33767152, 2021).
lung carcinoma (2 papers, 2021 to 2022). "LINC01354 is significantly increased in non-small cell lung carcinoma, promotes the proliferation and invasion of lung cancer cells, and high expression is related to advanced TNM stage and poor prognosis." (PMID 35303965, 2022).
thyroid cancer (2 papers, 2018 to 2020). "It was recently reported that dysregulation of LINC01354 in thyroid cancer is associated with genomic alterations." (PMID 33005105, 2020). "The results of CNV analyses showed that many differentially expressed lncRNAs loci are accompanied with copy number amplification or deletion, such as LINC01354 and LINC01341 have frequency gain, LINC00595 and LINC01519 have frequency loss in thyroid cancer." (PMID 29923329, 2018). "Moreover, some of those dysregulated lncRNAs genomic loci contains copy number amplification or deletion, such as LINC01354, LINC01341, LINC00595, and LINC01519, suggesting that genomic alterations might involve in part of these lncRNAs dysregulation in thyroid cancer." (PMID 29923329, 2018).
glioblastoma (1 paper, 2020). The most malignant astrocytic tumor (WHO grade IV). "Further validation by RT-qPCR revealed SMIM30, SNORA53 and LINC01354 were significantly upregulated and EFEMP2 markedly downregulated in 15 glioblastoma samples compared to 6 controls samples." (PMID 32962742, 2020).
liver cancer (1 paper, 2021). An epithelial or non-epithelial malignant neoplasm that arises from the liver. "As further verification of this finding, the difference in LINC02691, LINC02499, LINC01354, and NAV2-AS4 expression in liver cancer tissues (n = 371) was statistically significant (p < 0.05) compared with normal liver tissues (n = 50)." (PMID 34141458, 2021).
cancer (4 papers, 2019 to 2022). A tumor composed of atypical neoplastic, often pleomorphic cells that invade other tissues. "Some lncRNAs in the risk model, such as HAND2-AS1, LINC01354, and PGM5-AS1, have been reported to play vital roles in the progression of different cancers, while RP11-276H19.1 was identified for the first time." (PMID 35392086, 2022). "It has been known that lncRNAs participate in cancers though modulating gene expression and pathways, so we speculated that LINC01354 could regulate CRC through this way as well." (PMID 30987669, 2019). "The survival analysis showed that lncRNA AF186192.1, LINC01354 and WASIR2 might act as cancer suppressor genes regulated by DNA methylation to play significant roles in predicting the prognosis of LUAD." (PMID 31558162, 2019).
tumor (4 papers, 2019 to 2022). "Gain- and loss-of-function assays illustrated that LINC01354 acted as an oncogene in CRC to facilitate tumor cell proliferation, inhibited apoptosis, and promoted cell migration and invasion in an hnRNP-D/Wnt/β-catenin-dependent manner." (PMID 30987669, 2019). "Moreover, high level of LINC01354 expression is closely associated with tumor size, lymph node metastasis, TNM stage and distant metastasis." (PMID 30987669, 2019). "Combined with the results of gain- and loss-of-function assays, pathological and tumorigenic roles of LINC01354 were revealed, suggesting that LINC01354 promoted cell proliferation and migration/invasion and inhibited tumor cell apoptosis." (PMID 30987669, 2019). "Consistent with the in vitro findings, these results suggested that LINC01354 significantly promoted tumor growth, metastasis and epithelial-mesenchymal transition (EMT) in vivo." (PMID 30987669, 2019).
LINC01354 also shares sentences with these, for which no sentence is quoted: gastric carcinoma (1 paper); non-small cell lung carcinoma (1).